CASP1 (caspase 1)
Diseases named in the same sentence as CASP1 in open-access papers (continued):
Sharing a sentence is not in itself a finding about the gene and the disease.
Huntington disease (10 papers, 2013 to 2024). Huntington disease (HD) is a rare neurodegenerative disorder of the central nervous system characterized by unwanted choreatic movements, behavioral and psychiatric disturbances and dementia. "Aberrant RIP2 activity has been implicated as a driver of inflammation in diseases such as Huntington’s Disease, where it causes increased caspase-1 activation and IL-1β production, ultimately leading to neuronal cell death." (PMID 39483336, 2024). "In Huntington’s disease (HD) models, activation of caspase-1, -3, -8, and -9 as well as cytochrome c release were found in human striatal brain tissue." (PMID 35684455, 2022). "The activation of Caspase-1 exists in the brain of Huntington's disease (HD) patients and in HD mouse models, and the inhibition of caspase-1 in HD mouse models can slow down the progression of the disease." (PMID 35937897, 2022). "In a model of Huntington’s disease, minocycline delayed disease progression and mortality by inhibition of caspase-1 and caspase-3 up-regulation, enzymes which play an important role in the induction of necrosis and apoptosis." (PMID 26576678, 2015). "Mino inhibits caspase-1 mRNA expression in cerebral IR and a Huntington disease model." (PMID 24325836, 2013). "In Huntington’s disease, which is considered to be a sterile inflammatory disease, RIP2-mediated caspase-1 activation leads to chronic tissue inflammation and cell death." (PMID 39483336, 2024).
keratitis (10 papers, 2013 to 2025). A corneal disease that is characterized by inflammation of the cornea. "In line with this, in an animal model of P. aeruginosa-induced keratitis, mice deficient in caspase-1 and caspase-1/11 exhibit higher bacterial load and more severe corneal disease." (PMID 41304245, 2025). "Based on these findings, GSDMD and caspase-1 are potential novel therapeutic targets for A. fumigatus keratitis." (PMID 35655803, 2022). "Given the significance of pyroptosis in infectious keratitis, various classes of pyroptosis inhibitors, including caspase-1 inhibitors, have been developed to therapeutically target pyroptosis." (PMID 35655803, 2022). "In human corneal epithelial cells or mice keratitis models, P. aeruginosa upregulated the inflammasome as well as pyroptosis-associated genes and activated the NLRP3/caspase-1/IL-1β pathway." (PMID 35655803, 2022). "An earlier study had shown in a mouse model of P. aeruginosa keratitis that inhibition of caspase-1 as an adjuvant therapy in combination with ciprofloxacin reduced the severity of corneal inflammation." (PMID 35046947, 2021). "Although several reports in the cornea demonstrated the broad caspase-1 expression in neutrophils, macrophages, and corneal resident cells, neutrophils seem to be the predominant cell of caspase-1 expression in infectious keratitis model using NLRP3 KO mice." (PMID 31270454, 2019). "Our study demonstrated that TREM2 promotes host resistance against P. aeruginosa keratitis by inhibiting caspase-1-dependent pyroptosis, which provides new insights of TREM2-mediated anti-bacterial immunity." (PMID 29887864, 2018). "Previously, Hazlett’s group reported that knockout of caspase-1 (which is actually caspase-1 and caspase-11 double knockout), or treatment with caspase-1 inhibitor markedly decreases the ocular inflammation and bacterial load in P. aeruginosa keratitis." (PMID 29887864, 2018). "Western blot analysis showed that the protein levels of ASC, cleaved CASP1, N-GSDMD, cleaved IL-1β and cleaved IL-18 were all significantly elevated in C. albicans keratitis." (PMID 35463001, 2022). "In mice models of S. pneumoniae keratitis, the NLRP3 inflammasome (NLRP3, ASC, and caspase-1) was proven to be essential for cleavage and secretion of corneal neutrophil-derived IL-1β and bacterial clearance." (PMID 35655803, 2022). "In human corneal epithelial cells and mice models of A. fumigatus keratitis, pannexin 1 channels contributed to IL-1β expressions via NLRP3/caspase-1 inflammasome." (PMID 35655803, 2022). "Particularly, recent report indicated that neutrophil is the predominant cell in murine model of keratitis regarding NLRP3/ASC inflammasome and caspase-1 activation, and subsequent IL-1β processing." (PMID 31270454, 2019). "Preventing the production of IL-1β during P. aeruginosa keratitis by silencing the gene for ﻿the inflammasome NLRC4, inhibiting caspase-1 production (either using gene knockout mice or antibodies), or administering IL-1Ra (a natural inhibitor of IL-1β) reduces the clinical pathology of keratitis." (PMID 36422638, 2022). "Moreover, caspase-1 levels are significantly elevated in P. aeruginosa, Aspergillus fumigatus (A. fumigatus), and herpes simplex virus 1 (HSV-1) keratitis." (PMID 35655803, 2022). "In contrast, in a model of Pseudomonas induced keratitis utilizing B6 (susceptible) and NLRC4-/- (on the B6 background) mice, IL-1beta processing was found to be independent of NLRC4 or caspase-1 activity for both cytotoxic and invasive strains." (PMID 28961278, 2017). "However, we showed that in a murine model of P. aeruginosa keratitis, neutrophils mediate IL-1β secretion using serine proteases rather than caspase-1, although NLRP3 and ASC are reportedly expressed by neutrophils." (PMID 23750216, 2013).
non-small cell lung carcinoma (10 papers, 2017 to 2025). A group of at least three distinct histological types of lung cancer, including non-small cell squamous cell carcinoma, adenocarcinoma, and large cell carcinoma. "Blocking the histone methyltransferase G9A with BIX-01294 activates caspase-1, promoting apoptosis and reducing proliferation in non-small-cell lung cancer (NSCLC) cells." (PMID 40555741, 2025). "Polyphyllin VI induced caspase-1-mediated pyroptosis via the induction of the ROS/NF-κB/NLRP3/GSDMD signal axis in non-small-cell lung cancer." (PMID 34764819, 2021). "However, T0901317 15 a sulphonamide compound exerts its pyroptotic effects on non-small cell lung cancer (NSCLC) tumor cells by activating caspase-1 and NLRP3." (PMID 39316325, 2025). "The induction of caspase-1-mediated pyroptosis in non-small cell lung cancer (NSCLC) by Polyphyllin VI (PPVI) was seen via the signaling axis of ROS, nuclear factor kappa B (NF-κB), nod-like receptor family pyrin domain containing 3 (NLRP3), and gasdermin D (GSDMD)." (PMID 37998025, 2023). "GSDMD, CASP1, CASP4 and CASP5 gene expression are highly increased in PBMCs of non-small cell lung cancer patients and their expression are closely related to the clinical characteristics of patients." (PMID 37194012, 2023).
cerebral infarction (9 papers, 2018 to 2025). An ischemic condition of the brain, producing a persistent focal neurological deficit in the area of distribution of the cerebral arteries. "The effects of vx-765 inhibitor on pyroptosis-related molecules after MCAO were explored to investigate the protective effects of caspase-1 inhibition in cerebral infarction damage." (PMID 33584203, 2020). "MiR-17-5p mimic administration ameliorated TXNIP expression, NLRP3 inflammasome activation, caspase-1 cleavage, and IL-1β production, as well as brain infarct volume." (PMID 29394934, 2018). "SFN treatment of rats with middle cerebral artery occlusion inhibited the activation of inflammatory vesicles and the expressions of caspase-1, IL-1β and IL-18, reduced the volume of cerebral infarction, improved the score of neurological function, and reduced neutrophil infiltration." (PMID 34526897, 2021). "Both NADPH and Apocynin inhibit the expression of NLRP3, ASC, caspase-1, IL-1β, and IL-18 in the ischemic cerebral cortex in a rat cerebral infarction model, and reduce the volume of cerebral infarction, improve survival after infarction, and restore neurological function." (PMID 34526897, 2021). "In addition, we also noticed that in the results of cerebral infarction volume measurement and TUNEL staining, there were differences between C57 mice and Cas-1 ko mice in the EA group, and the only factor causing these differences was caspase-1 knockout." (PMID 35600074, 2022). "However, the role of caspase-1-mediated BBB dysfunction in cerebral infarction remains unknown." (PMID 33584203, 2020). "Calycosin significantly reduced neurological impairments and brain infarction in a dose-dependent manner, alleviated neuronal damage and decreased the expression of pyroptosis-related markers, including NLRP3, GSDMD, HMGB1, IL-1β, IL-18, and caspase-1." (PMID 40606597, 2025). "Additionally, inhibition of caspase-1 induces anti-inflammatory and anti-apoptotic processes, shown to alleviate neuronal damage in the hippocampal CA1 region after cerebral infarction." (PMID 33584203, 2020). "EA at LU5, LI4, SP6 and ST36 could decrease the score of neurological deficit, reduce the volume of cerebral infarction and improve the degree of nerve cell injury, and inhibit NLRP3, pro-caspase-1, cleaved-caspase-1 p20, pro-IL-1β, cleaved-IL-1β and GSDMD protein expression." (PMID 36925735, 2023). "Results showed that EA could reduce the score of neurological deficit, reduce the volume of cerebral infarction and improve the degree of nerve cell injury, and inhibit NLRP3, pro-caspase-1, cleaved caspase-1 p20, pro-IL-1β, cleaved IL-1β, and GSDMD protein expression." (PMID 35600074, 2022). "However, it is not clear whether inhibition of caspase-1 can preserve blood-brain barrier (BBB) integrity following cerebral infarction." (PMID 33584203, 2020).
fungal infection (9 papers, 2017 to 2024). "It was found that 24-h fungal infection caused a decrease in caspase-1 activity in G. mellonella hemolymph, and that this correlated with changes in eicosanoid concentration." (PMID 35069239, 2021). "WT BMDMs released a significant amount of IL-18 after fungal infection, whereas the Casp1/11–/–Ripk3–/–Casp8–/– BMDMs released significantly less." (PMID 33109609, 2020). "Caspase-1 and caspase-8 are required for IL-1β processing and secretion during this fungal infection." (PMID 31425553, 2019). "The caspase-1-dependent cytokines exert important effects in the initiation of the adaptive Th1 and Th17 cellular responses to fungal infections." (PMID 28740491, 2017). "In contrast, Nlrp3−/−, Casp1/11−/−, and Asc−/− mice showed a prevalent Th2/Th3/Treg profile of response that was unable to control the fungal infection." (PMID 28740491, 2017). "Of note, Casp-1-/- mice survived longer than Nlrp3-/- mice after fungal infection." (PMID 34912336, 2021). "Moreover, western blot analysis revealed dramatically decreased levels of pyroptosis-associated proteins ASC, cleaved CASP1, GSDMD, cleaved GSDMD, cleaved IL-1β and cleaved IL-18 in the Ad-NLRP3-shRNA group compared with the Ad-GFP-shRNA group during fungal infection." (PMID 35463001, 2022). "During fungal infection, the NLRP3 inflammasome formation in immune cells leads to the activation of CASP1, which then cleaves the proinflammatory cytokines IL-1β and IL-18 to their bioactive forms and induces pyroptosis." (PMID 35463001, 2022). "During fungal infection, the activation of the NLRP3-ASC-CASP1 inflammasome leads to cleavage of pro-CASP1, which then processes the proinflammatory cytokines IL-1β and IL-18 to their bioactive forms and cleaves GSDMD to trigger pyroptosis." (PMID 35463001, 2022). "Followed by priming, the proteolytic cleavage of pro-IL-1β into its mature form is canonically performed by the protease caspase-1, and this process is largely dependent on the assembly of the NLRP3 inflammasome in fungal infections." (PMID 29209318, 2017). "NLRP3 functions as a pattern recognition receptor (PRR) that recognizes pathogen-associated molecular patterns (PAMPs) from bacterial, viral and fungal infections among others and that, together with the adaptor ASC/PYCARD protein and caspase-1, form the NLRP3 inflammasome." (PMID 39591118, 2024).
hyperuricemia (9 papers, 2012 to 2024). An abnormally high level of uric acid. "In this study, we found that NLRP3, cleaved caspase-1 were increased in the heart tissue of hyperuricemia mice." (PMID 36986461, 2023). "Medium - and high-dose groups also reduced NLRP3, ASC, and Caspase-1 protein overexpression in hyperuricemia model cells." (PMID 36120294, 2022). "The protein expression of NLRP3, ASC, and Caspase-1 in the kidney tissue of hyperuricemia mice and the level of mice inflammatory cytokines NLRP3 and IL-1β was significantly reduced; this change was demonstrated at each dose in the dosing groups." (PMID 36120294, 2022). "In another investigation, the NLRP3, ASC, caspase-1 gene and protein expression in PBMCs, and the IL-1β and IL-18 protein concentrations in plasma of patients with hyperuricemia and patients with UAN were significantly higher compared to healthy controls." (PMID 35204131, 2022). "For example, Shizhifang effectively suppresses the NLRP3-ASC-caspase-1 axis through accommodating the ROS pathway, thereby alleviates potassium oxonate - induced hyperuricemia." (PMID 33568990, 2020). "Uric acid (UA) activates the NLRP3-ASC-caspase-1 axis and triggers cascade inflammatory that leads to hyperuricemic nephropathy and hyperuricemia-induced renal tubular injury." (PMID 29358971, 2017). "Subsequently, Caspase-1 inhibition by quercetin and allopurinol prevented kidney IL-1β and IL-18 release and over-production triggered by hyperuricemia and dyslipidemia in this model." (PMID 22701621, 2012). "A recent study shows that hyperuricemia triggers activation of Caspase-1 in RTECs50." (PMID 39433541, 2024). "The results showed that the protein expression levels of NLRP3, Caspase-1, and ASC were significantly increased in both renal tissues of hyperuricemia mice and adenosine-treated HK-2 cells." (PMID 36120294, 2022). "In these analyses, the plasma IL-1β concentrations and the PBMC caspase-1 and ASC gene and protein expression were significantly higher in UAN compared to hyperuricemia patients." (PMID 35204131, 2022). "Potassium oxonate-induced hyperuricemia mice developed the elevated levels of liver XOD and renal ASC, Caspase-1, NLRP3, and GLUT9 protein and depressed OAT1 and OAT3 protein levels (all p < 0.05) compared with normal control mice." (PMID 36120294, 2022).
infarction (9 papers, 2020 to 2025). A localised pathological necrosis of tissue resulting from obstruction of the blood supply usually by a thrombus, an embolus, or vascular torsion. "They found that the NLRP3 inflammasome inhibitor MCC950 significantly reduced cerebral infarct volume, inhibited caspase-1 activation, attenuated inflammation, and stabilized the blood-brain barrier, thereby preventing I/R injury." (PMID 40606597, 2025). "Caspase 1 inhibitor VX‐765 immediately before reperfusion preserved cardiac function, reduced infarction and inflammation in I/R rats." (PMID 39929748, 2025). "Caspase 1 inhibitor VX‐765 treatment in the extremely early stage (10 min) of AMI significantly reduces the infarction region in AMI mice." (PMID 39929748, 2025). "Caspase-1 is a critical component of the NLRP3 inflammasome that regulates cardiac remodeling post-infarction, whereas its role in rejection is unknown." (PMID 37781362, 2023). "In addition, NLRP3, caspase-1 cleavage, and particularly IL-1β were induced early during myocardial ischemia/infarction." (PMID 34752417, 2022). "Results showed that AM-SB significantly reduced infarction volume, inflammation (IL-1β, TNF-α), and pyroptosis-related markers (NLRP3, GSDMD, ASC, Caspase-1), while decreasing gliosis and improving cerebral metabolites." (PMID 39859214, 2025).
lung adenocarcinoma (9 papers, 2014 to 2025). A carcinoma that arises from the lung and is characterized by the presence of malignant glandular epithelial cells. "Our focus was constructing a diagnostic and prognostic model for lung adenocarcinoma based on the core genes—CASP1, NLRP3, AIM2, and NLRP1." (PMID 40026444, 2025). "We further analyzed the influence of core genes on lung adenocarcinoma prognosis, and survival analysis revealed a significant association between CASP1, NLRP3, NLRP1, and AIM2 and overall survival in patients with lung adenocarcinoma." (PMID 40026444, 2025). "The results showed that CASP1, NLRP3, AIM2, and NLRP1 exhibited excellent diagnostic efficacy, suggesting their potential utility as diagnostic biomarkers for lung adenocarcinoma." (PMID 40026444, 2025). "CASP1, NLRP3, AIM2, and NLRP1 are core pyroptotic genes in lung adenocarcinoma, significantly associated with immune cell infiltration, diagnosis, and prognosis in this condition." (PMID 40026444, 2025). "With the aid of TIMER2.0 database, we found that TRAF3 was positively correlated with the expression of ASC (R = 0.09, P<0.05), caspase-1 (R = 0.32, P<0.01) and IL-1β (R = 0.37, P<0.01) in lung adenocarcinoma." (PMID 37798663, 2023). "We first analyzed the correlation between TRAF3 and pyroptosis-related genes through TIMER2.0 database, the results showed that TRAF3 was positively correlated with the expression of ASC, caspase-1 and IL-1β in lung adenocarcinoma." (PMID 37798663, 2023). "Based on the existing results, we preliminarily concluded that TRAF3 plays a tumor inhibitory role in lung adenocarcinoma, in part by mediating caspase-1-dependent pyroptosis." (PMID 37798663, 2023). "For example, long non-coding RNA SNHG5 regulates gefitinib resistance in lung adenocarcinoma cells by targeting the miR-377/CASP1 axis." (PMID 30250399, 2018). "Evaluation using ROC curves for core genes indicated that CASP1, NLRP3, AIM2, and NLRP1 demonstrate excellent diagnostic potential for lung adenocarcinoma and may serve as diagnostic markers for the disease." (PMID 40026444, 2025). "It suggests that TRAF3 may inhibit the development of lung adenocarcinoma by regulating the caspase-1-dependent pyroptosis signaling." (PMID 37798663, 2023). "Finally, high expression of G9A or low expression of CASP1 is correlated with poor overall survival in lung adenocarcinoma." (PMID 28383547, 2017). "Finally, we analyzed whether G9A or CASP1 could serve as prognostic biomarkers in lung adenocarcinoma (LUAD)." (PMID 28383547, 2017). "This further confirms the pyroptosis core gene CASP1, NLRP3, AIM2, and NLRP1 expression levels in lung adenocarcinoma and their connection to immune infiltration." (PMID 40026444, 2025). "Our findings suggest that TRAF3 inhibition can facilitate the proliferation and migration of lung adenocarcinoma cells, and reduce the sensitivity of LUAD cells to paclitaxel, partly by mediating the caspase-1-dependent pyroptosis." (PMID 37798663, 2023). "The low expression of CASP1 is related to the poor prognosis of lung adenocarcinoma, and CASP1 inhibits the invasion and migration of the non-small cell lung cancer (NSCLC) cells." (PMID 36244998, 2022). "Conversely, activation of the NLRP3 inflammasome promotes the proliferation and migration of lung adenocarcinoma A549 cells, which is related to the ability of the NLRP3 inflammasome to mediate the release of IL-18 and IL-1β through caspase-1-dependent or caspase-1-independent pathways." (PMID 35246158, 2022).
metabolic syndrome (9 papers, 2012 to 2025). A cluster of metabolic risk factors for CARDIOVASCULAR DISEASES and TYPE 2 DIABETES MELLITUS. "Based on these findings, we conclude that Caspase-1 is a potential target for treating dyslipidemia by regulating pyroptosis." (PMID 40582769, 2025).